LAMB2 (laminin subunit beta 2)
Diseases named in the same sentence as LAMB2 in open-access papers (continued):
Sharing a sentence is not in itself a finding about the gene and the disease.
ovarian carcinoma (3 papers, 2014 to 2021). A malignant neoplasm originating from the surface ovarian epithelium. "A previous study revealed that the downregulation of LAMB2 caused by HE4 gene interference results in the invasion and metastasis of ovarian cancer cells." (PMID 34917619, 2021). "Our findings indicated that MAP kinase interacting serine/threonine kinase 2 (MKNK2) and laminin beta 2 (LAMB2) gene expression levels were downregulated in response to HE4 interference in ovarian cancer cells, whereas exogenous HE4 protein supplementation reversed this effect." (PMID 25362534, 2014).
Alport syndrome (2 papers, 2014 to 2018). A rare renal disease characterized by glomerular nephropathy with hematuria progressing to end-stage renal disease (ESRD), frequently associated with sensorineural deafness, and occasionally with ocular anomalies. "Changes in one component of the GBM can affect others, for example in Alport’s syndrome, where mutations in collagen IV result in ectopic expression of laminin 51; however, Lamb2−/− mice have normal collagen IV chain expression." (PMID 24293254, 2014).
developmental delay (2 papers, 2020 to 2025). "Following presentation with recurrent macroscopic hematuria and albuminuria, compound heterozygous mutations in LAMB2, encoding laminin β2, were identified in a boy with short stature, visual impairment, and developmental delay." (PMID 31769495, 2020).
Diffuse mesangial sclerosis (2 papers, 2015 to 2020). Thickening and scarring (sclerosis) of the mesangium (a structure in the glomerulus). "Diffuse mesangial sclerosis has been identified in 61% of individuals with LAMB2-associated NS." (PMID 32467597, 2020). "Diffuse mesangial sclerosis is associated with dominant pathogenic variants in WT1 (23.1%) and biallelic pathogenic variants in PLCE1 (17.8%), LAMB2 (13.6%), and NPHS1 (4.9%)." (PMID 32467597, 2020).
prostate carcinoma (2 papers, 2010). A carcinoma that arises from epithelial cells of the prostate gland. "LAMB2 might be involved in the cell adhesion or motility of prostate cancer cells." (PMID 20969748, 2010). "Alterations of the gene profile of LAMB2 and CDKN2C/p18(Ink4c), a CDK4 inhibitor, have been reported on the transition from prostatic intraepithelial neoplasia (PIN) to prostate cancer." (PMID 20805891, 2010). "The down-regulation of LAMB2 and MEF2C might be involved with cell adhesion or motility in invasive prostate cancer cells and apoptosis via BCL2 transformation, respectively." (PMID 20969748, 2010).
alcohol dependence (1 paper, 2025). Physical and psychological dependence on alcohol. "The detection of proteins involved in the neurovascular system such as endothelial cells (VE-cadherin), pericytes (ACTA), and basement membrane (LAMB2, fibulins) suggests that alcohol dependence affects all components of the BBB architecture." (PMID 41292811, 2025).
atherosclerosis (1 paper, 2025). A disease characterized by the build-up of fatty material and calcium deposition in the arterial wall resulting in partial or complete occlusion of the arterial lumen. "In atherosclerosis, ECs communicated extensively with pericyte cells and SMCs through LAMININ (LAMA5-(ITGA1+ITGB1), LAMA5-(ITGA7+ITGB1), LAMB2-(ITGA6+ITGB4), LAMB2-(ITGA6+ITGB1)) and COLLAGEN (COL4A1-(ITGA1+ITGB1), COL4A2-(ITGA1+ITGB1)) pathways." (PMID 40225569, 2025).
cervical cancer (1 paper, 2023). A primary or metastatic malignant neoplasm involving the cervix. "Meanwhile, there is a negative correlation between the expression levels of hsa‐mir‐133a‐2 and LAMB2, and LAMB3 could reverse hsa‐mir‐133a‐2 inhibitory effect on cervical cancer cell proliferation and invasion." (PMID 36305754, 2023).
cobblestone lissencephaly (1 paper, 2025). "Mutations in ECM-related genes, including POMT1/2 and laminin subunit genes, LAMB2, and LAMC3, are associated with conditions such as cobblestone lissencephaly and polymicrogyria, leading to cortical layer disorganization and abnormal cortical folding." (PMID 41219193, 2025).
congenital muscular dystrophy (1 paper, 2021). A muscular dystrophy that is characterized by diminished muscle tone (hypotonia), progressive muscle weakness and degeneration (atrophy), abnormally fixed joints, spinal rigidity, and delays in reaching motor milestones such as sitting or standing unassisted. "Mutations of LAMA2 and LAMB2 cause congenital muscular dystrophy (muscle atrophy) in embryos." (PMID 33809502, 2021).
COVID-19 (1 paper, 2023). A disease caused by infection with severe acute respiratory syndrome coronavirus 2. "The most changed components of BM included laminins (LAMB2, LAMA2, LAMC3, LAMB1, LAMC1, and LAMA5) and proteoglycans (COL18A1, HSPG2, and AGRN), with some BM specific collagens (IV, VIII, XVIII, and V collagens) remaining in COVID-19 brains, as compared with the control brains." (PMID 36609561, 2023).
diabetes (1 paper, 2024). "In addition to the increased expression of the ECM protein COL4A6, LAMB2, and HIC5 (encoded by Tgfb1i1) are also present in the livers of mice with late-stage diabetes and HFD/STZ." (PMID 39494341, 2024).
end-stage renal disease (1 paper, 2017). "The features of CNS with rapid progression to end-stage renal disease in our infant agreed with previous observations that severe PS in most patients is caused by homozygosity or compound heterozygosity for truncating LAMB2 mutations." (PMID 28683731, 2017).
hearing loss (1 paper, 2017). "Further study with more patients will be necessary to evaluate the clinical incidence and features of hearing loss under LAMB2 deficiency." (PMID 28683731, 2017).
Hypertension (1 paper, 2018). The presence of chronic increased pressure in the systemic arterial system. "The mechanism of FAM110A, PREP, ANKRD9, DCPS, WFDC12, TPTE, and LAMB2 genes on the occurrence and development of hypertension is not yet clear." (PMID 29379041, 2018).
liver fibrosis (1 paper, 2024). "In addition, ligand-receptor pair analysis revealed that aHSC could interact with hepatocytes and Cd36+ KCs via the Lamb2/Dag axis, which have been demonstrated to be associated with liver fibrosis." (PMID 39494341, 2024).
MELAS (1 paper, 2024). "Inherited retinal degeneration and retinal atrophy occurred with pathogenic variants in LAMB2 and with mitochondrial variants (COQ2, COQ8B, MELAS, MIDD, Kearns–Sayre disease)." (PMID 37578539, 2024).
minimal change disease (1 paper, 2019). "Nephrotic diseases studied included minimal change disease in human biopsies, Heymann nephritis in a rat model, Lamb-2, and Cd2ap mouse knockout models and an Adriamycin injury mouse model." (PMID 30899761, 2019). "The authors demonstrated this with 3 mouse models (Cd2ap-KO, Lamb2-KO, and Adriamycin) and 3 examples of human nephrotic disease (minimal change disease, FSGS, and diabetic nephropathy)." (PMID 30899761, 2019).
pancreatic cancer (1 paper, 2016). "Our analysis showed that the expression of LAMB2 was different among our two pancreatic cancer cell lines." (PMID 27869176, 2016).
preeclampsia (1 paper, 2021). Preeclampsia is a hypertensive disorder of pregnancy that is characterized by new-onset hypertension with proteinuria presenting after 20 weeks of gestation, and depending on mild or severe forms may initially present with severe headache, visual disturbances, and hyperreflexia. "Among these genes, LAMB2, PTK2, RAC1, QSOX1, FN1, and VCAM1 have known associations with the pathogenic mechanisms of preeclampsia." (PMID 35719905, 2021).
prostate intraepithelial neoplasia (1 paper, 2019). A neoplastic proliferation of the epithelial cells that line the acini and the ducts of the prostate gland. "Laminin subunit beta 2 (LAMB2) has been identified as being downregulated in the transition from prostate intraepithelial neoplasia to invasive prostate cancer from differential expression analysis." (PMID 30988330, 2019).
synucleinopathy (1 paper, 2025). A neurodegenerative disease that is characterized by the abnormal accumulation of aggregates of alpha-synuclein protein in neurons, nerve fibers or glial cells. "Instead, we demonstrated the suppression of other microglial mobility/phagocytosis-associated genes such as Icam2, Acta2, Fos, Fosb, Egr1, Lamb2 and Tpm2 in both synucleinopathy patients and the animal model." (PMID 41258081, 2025).
cancer (10 papers, 2012 to 2025). A tumor composed of atypical neoplastic, often pleomorphic cells that invade other tissues. "The main site of the LAMB2-RPSA interaction was more restricted to the cancer-associated fibroblast (CAF) niche than to the cancer cell niche, represented by the fold change (FC) of the average Jcomp of CAF to cancer cell niche in ER + tissues of 2.763." (PMID 40170080, 2025). "LAMB2 (laminin subunit beta 2): Although its expression has been associated with some carcinomas, ts expression is tightly regulated in normal human tissues and in disease." (PMID 31616468, 2019). "Among those genes, we found up-regulation of αSma/Acta2, a marker of activated and cancer-associated fibroblasts, and Nidogen-2, Lamb2, and Prelp, which encode for ECM-associated proteins." (PMID 29725010, 2018). "For example, the cancer basal cells exclusively used the beta-2 subunit (LAMB2) in the older cohort." (PMID 39483921, 2024). "Subunit gamma-1 (LAMC1) was downregulated in all four cancer types, while all other subunits showed lower expression levels in SCLC; LAMC2, LAMA5, LAMB2 in LCC; and LAMA5, LAMB2, LAMA3 in AC as well." (PMID 35681609, 2022). "On the other hand, a new set of potential biomarkers (NCKAP1, TNFRSF12A, LAMB2, FKBP9, PFN2, TOM1L1) and expression rules for the identification of different cancers at the transcriptome level were discovered." (PMID 34917619, 2021). "Meanwhile, other cell-cell adhesion-related molecules, such as laminins (LAMA4, LAMA5, LAMB1, LAMB2 and LAMC2) and integrins (ITGA5, ITGA5, ITGB5, ITGA11 and ITGBL1), are elevated in cancer tissues." (PMID 22905095, 2012).
tumor (10 papers, 2011 to 2024). "A second common protein exhibiting a decreased abundance in all tumor sources was laminin subunit beta-2 (LAMB2)." (PMID 32867073, 2020). "Of all CNA gene gains and losses, the PI3K-Akt Pathway enlisted 264 genes of which RAF1 (16 times lost), ITGA9 (15 times lost) and LAMB2 (15 times lost) were abundantly affected in HRO G1 ccRCC tumour samples." (PMID 28486536, 2017). "LAMB2 (ENSG00000172037) encodes a subunit of laminins, which are one of the major glycoproteins present in the basement membrane of the extracellular matrix and are related to tumor angiogenesis, invasion, and metastasis." (PMID 34917619, 2021). "Regarding pathway assignments of at least 20 HRO tumours, 10 top-ranked genes, of which 9 were lost in 3p, were linked with 7 to 45 pathways (n = 280) comprising RAF1 (45 PWs), RHOA (25 PWs), IPTR1 (22 PWs), CACNA1D, ITGA9 (8PWs), WNT7A (8 PWs) TLR9 (7PWS9, LAMB2 (7 PWs) and ARPC4 (6 PWs)." (PMID 28486536, 2017). "The role of five of them (LAMB2, SERPINEE1, ITGB1, TNC, and LAMA5) in tumor growth has been well established." (PMID 35642785, 2022). "The tumor suppressor miR-200 affects EMT and tumor cell metastasis by modulating the cell adhesion molecule E-cadherin and the ECM proteins COL6A1, LAMA5, LAMB2, LAMC2, and Fibronectin." (PMID 34769264, 2021). "Our investigations identified three major invasiveness biomarkers common to the three tumor sources, CAPG, FABP4, and LAMB2, and an additional set of 25 candidate biomarkers shared by rat and patient tumors." (PMID 32867073, 2020). "Between these two genes, FN1, but not LAMB2, was expressed in a higher level in bone metastasis comparing to primary tumor and metastases in other organs using human datasets, suggesting a specific involvement of FN1 in bone-metastatic PC." (PMID 36749798, 2023). "Our investigations identified three major invasiveness biomarkers not documented so far in integrative molecular studies characterizing MM, common to the three tumor sources, CAPG, FABP4, and LAMB2, and an additional set of candidate biomarkers shared by rat and patient tumors." (PMID 32867073, 2020). "Furthermore, we demonstrated that ZIC1 can suppress the expression of other novel genes (TACSTD2, ANGPT2, LAMB2, LAMB3 and MALAT1 etc.)related to tumor angiogenesis and metastasis." (PMID 21347233, 2011).
kidney disease (6 papers, 2014 to 2025). "It has been well documented that monoallelic LAMB2 variants can increase the rate of kidney disease progression in murine models of AS." (PMID 40003707, 2025). "Recently, mutations in the LAMB2 gene have been identified in patients with kidney disease who lack noticeable extrarenal manifestations." (PMID 39416865, 2024). "In fact, pathogenic variants in various genes responsible for inherited kidney diseases (patients with NPHS1, EYA1, LAMB2, and CLCN5 gene mutations) were detected by NGS in our study." (PMID 31364286, 2019).
neuromuscular disease (2 papers, 2009 to 2014). "Thus, the extensive analysis performed in Lamb2−/− and the conclusions drawn from this animal model provide an invaluable key to understanding the pathogenesis of the human neuromuscular disease reported here." (PMID 19251977, 2009).
neurological disorders (1 paper, 2009). "These include genital abnormalities (WT1), eye defects (LAMB2), and neurological disorders (Mowat–Galloway)." (PMID 17968594, 2009).
LAMB2 also shares sentences with these, for which no sentence is quoted: cognitive defects (2 papers); Denys-Drash syndrome (2); genetic disease (2); Nephropathy (2); Neurodevelopmental delay (2); albuminuria (1); aniridia (1); basal cell carcinoma (1); breast carcinoma (1); channelopathies (1); Cholecystitis (1); chordoma (1); coloboma (1); congenital nephrosis (1); Dent disease (1); duodenal tumor (1); dystroglycanopathies (1); endometriosis (1); epilepsy (1); esophagitis (1); Fabry disease (1); fatty liver (1); Frasier syndrome (1); glioblastoma (1); glomerulosclerosis (1); Hyphema (1); hypopituitarism (1); Lowe syndrome (1); metastatic cancer (1); metastatic tumor (1).
A further 16 diseases each share a sentence with LAMB2 in 1 paper.